EZR (ezrin)
Diseases named in the same sentence as EZR in open-access papers (continued):
Sharing a sentence is not in itself a finding about the gene and the disease.
infection (continued). "Considering the major role of S in virus entry and membrane fusion, we first assessed whether S endodomains could be accessible to ezrin at early stages of infection." (PMID 23185364, 2012). "However, a significant decrease (twofold) in the number of filopodia was observed on cell transfected with dominant-negative ezrin compared with control cells transfected with wild-type ezrin 30 min post infection." (PMID 19046338, 2009). "Specifically, when cells were treated with CHE chloride prior to infection with this pathogen, there was a significant decrease in the movement of ezrin from the detergent-soluble to the detergent-insoluble (cytoskeletal) fraction, which is a marker of ezrin activation." (PMID 40565258, 2025). "The specific role of ezrin in the formation of the phagocytic cup is supported by a recent report showing that ezrin (but not moesin) promotes the formation of functional phagocytic cup-like invasive structures during infection of mammalian cells by extracellular amastigotes of Trypanosoma cruzi." (PMID 32098334, 2020). "The fact that the replication level measured by qRT-PCR was slightly lower in the clone expressing the FERM domain of ezrin than control cells at 24 hours post-infection suggests that although ezrin restricts the rate of infection at early time points, its function may be important for later stages." (PMID 23185364, 2012). "Indeed, an identical phenotype (i.e. rapid filopodia withdrawal with increased proportion of pedestals) was seen after infection of 3T3 cells with EPEC expressing MapΔTRL or infection of 3T3 cells transfected with dominant-negative RhoA or ezrin with E2348/69 Δmap overexpressing MapEPEC." (PMID 19046338, 2009). "Concurrently, the expression of the phosphorylated forms of Src (pSrc), Ezrin (pEzrin), and Cav-1 (pCav-1) is significantly upregulated at 15 and 30 min post-EMCV infection, reaching a peak at 15 min." (PMID 40631914, 2025). "The phosphorylation level of the actin-binding protein ezrin (EZR), which is involved in microvilli formation, and the protein level of the microvilli core protein, EBP50, were significantly increased after infection." (PMID 36918546, 2023). "We have previously reported that ezrin silencing attenuates infectivity of released HIV-1 vector particles containing HIV-1 Env protein, suggesting that HIV-1 Env-mediated infection requires ezrin expressed in HIV-1 vector-producing cells." (PMID 32411688, 2020). "At 3 h post infection (hpi), over 60% of N. cinerea microcolonies co-localised with actin, CD44 or ezrin." (PMID 32208456, 2020). "At the cellular level, proteins like ICAM-1, TLR2 or Ezrin/Radixin were only up-regulated in CACs treated with the serum of asymptomatic patients at the highest peak of infection (PCR + /IgG −), but not with the serum of PCR −/IgG + individuals." (PMID 35397534, 2022). "The activation and recruitment of ezrin to GC adherent sites of non-polarized T84 cells suggest a role for ezrin in GC-induced actin reorganization and GC infection." (PMID 34852011, 2021). "Immunoblotting showed that after PAO1 infection, the levels of total and phosphorylated STAT3 were increased in the Ezrin-silenced MH-S cells, indicating that Lyn indeed regulates the STAT3 activation by binding Ezrin." (PMID 29263906, 2016). "To ascertain whether ICAM-1 regulates the Src-Ezrin-Cav-1 pathway via Src to jointly regulate EMCV internalization, we initially analyzed the viral titers in both wild-type (WT) BHK-21 cell lines and ICAM-1 KO BHK-21 cell lines following EMCV infection." (PMID 40631914, 2025). "Ezrin clearly localized in MV in non-infected cells or in cells prior to infection." (PMID 38894970, 2024). "Ezrin protein may be required for the HIV-1 Env-meCAGAATAATCGCGAGdiated infection but not VSV-G-mediated infection." (PMID 32411688, 2020).
bacterial infection (4 papers, 2016 to 2025). "We for the first time demonstrate that during bacterial infection, a Lyn–IL-6R–Ezrin complex negatively regulates the IL-6/STAT3 signaling pathway in murine AMs." (PMID 29263906, 2016). "In addition, vitamin D may protect the vagina from bacterial infection by increasing the stability, proliferation and differentiation of stratified squamous epithelial cells through activation of the VDR, p-RhoA and p-Ezrin pathways, as suggested in other systems." (PMID 40469676, 2025).
adenocarcinoma (2 papers, 2010 to 2022). A common cancer characterized by the presence of malignant glandular cells. "Ezrin was also expressed in the intercalated ducts in the pancreatic tissue that was adjacent to the adenocarcinoma, which was considered to be the origin in the pancreatic ducts and acini, as well as the starting point of PDAC development." (PMID 20569470, 2010). "We also observed that ezrin was expressed in the intercalated duct cells in pancreatic tissue adjacent to the adenocarcinoma." (PMID 20569470, 2010).
inflammation (2 papers, 2016 to 2024). Aberrant reaction of the microcirculation characterized by movement of fluid and leukocytes from the blood into extravascular tissues. "Further, delivery of a Moesin phospho-null mutant into murine lung endothelium attenuated LPS-induced lung inflammation and vascular leak suggesting that MLCP opposes LPS-induced ALI by mediating the dephosphorylation of Moesin and Ezrin." (PMID 27976727, 2016).
kidney disease (2 papers, 2011 to 2024). "The findings of this study enhance our comprehension of Ezrin's regulatory mechanisms and further elucidate the physiological significance of lactate modification in renal diseases." (PMID 38767134, 2024).
intestinal diseases (1 paper, 2016). "It has been suggested phosphorylation of Ezrin will regulate the early events in brush border induction and loss of microvilli and brush border lead to common features of several intestinal diseases." (PMID 27895852, 2016).
EZR also shares sentences with these, for which no sentence is quoted: Sepsis (4 papers); breast (3); serous ovarian carcinoma (3); Autoimmunity (2); cancer thyroid (2); cervical adenocarcinoma (2); chronic pancreatitis (2); coronary heart disease (2); dementia (2); gynecologic cancer (2); hepatitis B (2); nephrosis (2); neurodegenerative disease (2); oral squamous cell carcinoma (2); pancreatic adenocarcinoma (2); Pleural effusion (2); actinic keratosis (1); acute lymphoblastic leukemia (1); age (1); allergic rhinitis (1); Arthritis (1); atopic dermatitis (1); Atrophy (1); basal cell carcinoma (1); blood cancers (1); bone metastasis (1); Bowen's disease (1); breast adenocarcinoma (1); Burkholderia mallei Infection (1); cardiomyopathy (1).
A further 61 diseases each share a sentence with EZR in 1 paper.